PHLDA1 (pleckstrin homology like domain family A member 1)
Diseases named in the same sentence as PHLDA1 in open-access papers (continued):
Sharing a sentence is not in itself a finding about the gene and the disease.
cancer (continued). "Even more importantly, ERK-induced PHLDA1/2 expression serves as a double-edged sword for cancer prevention and treatment." (PMID 35831322, 2022). "Coadministration of bortezomib overcomes this drug resistance by disrupting PHLDA1/2-mediated, cancer-specific ERK-AKT crosstalk." (PMID 35831322, 2022). "PHLDA1 was also found to express in many types of cancer, such as brain, liver, bladder, and lung cancer." (PMID 35237256, 2022). "Conversely, single depletion of endogenous PHLDA1 or PHLDA2 by their specific siRNAs only slightly enhanced AKT activity in cancer cells, whereas their co-depletion resulted in a much greater increase in AKT activity." (PMID 35831322, 2022). "To investigate PHLDA1/2 roles in cancer, we first quantitatively compared the capacities of individual PHLDA proteins to suppress AKT activity." (PMID 35831322, 2022). "These combined findings indicate that pharmacological inhibition of oncogenic ERK signaling in cancer induces the transactivation of AKT through PHLDA1/2 downregulation, thereby leading to resistance of cancer cells to ERK pathway inhibitors." (PMID 35831322, 2022). "Analyses of large-scale cancer genomics datasets showed significantly higher expression of PHLDA1/2 mRNAs in various cancers than in their corresponding normal tissues." (PMID 35831322, 2022). "The combined expression of PHLDA1/2 is critical to confer resistance to ERK pathway-targeted therapeutics on cancer cells." (PMID 35831322, 2022). "In vitro studies about the roles of PHLDA1 in cancer cell proliferation and survival showed equivocal results, some studies provided evidence for a pro-apoptotic and/or anti-proliferative role 5,8 and others suggested the opposite role 9-12." (PMID 34405011, 2021). "PHLDA1 has been reported to be expressed in numerous cancers and has different functions in different cancers, most of which are correlated with cell proliferation and apoptosis." (PMID 32983961, 2020). "PHLDA1 expression levels in remaining tumors in these mice were decreased compared to controls, again suggesting that chemoresistance is developed in cancer cells due to aberrantly activated AKT signaling upon downregulation of PHLDA1." (PMID 32429563, 2020). "We have identified PHLDA1 downregulation as a mechanism by which cancer cells can develop resistance to RTK-targeted therapy." (PMID 29490281, 2018). "use unbiased transcriptomic and phosphoproteomic analysis to identify PHLDA1 as a mediator of acquired resistance to kinase-targeted therapies in cancer." (PMID 29490281, 2018). "Finally, to broaden the application of PHLDA1, we analyzed its applicability across various types of cancer." (PMID 40688078, 2025). "The PHLDA1 protein plays essential roles in cancer, depending on the cellular type and context." (PMID 39630301, 2025). "PHLDA1 expression may be reduced in certain types of cancer, potentially contributing to uncontrolled cancer cell growth." (PMID 41430389, 2025). "Through additional pan-cancer analysis tests, we investigated the function of PHLDA1." (PMID 40688078, 2025). "Therefore, the influence of PHLDA1 and Tollip regulation is also worth further investigation in the context of cancer." (PMID 39630301, 2025). "Finally, the correlation analysis uncovered that angiogenesis, cell cycle, and EMT were significantly positively correlated with PHLDA1 in all types of cancer, further suggesting the cancer-promoting role of PHLDA1." (PMID 40688078, 2025). "PHLDA1 was evaluated as a prognostic marker in several types of cancer." (PMID 39630301, 2025). "In particular, tissue-specific microenvironmental cues and distinct oncogenic drivers in each cancer type may confound the generalizability of PHLDA1’s functional role." (PMID 40688078, 2025). "Some functions of PHLDA1 in cancer are already indicated by other studies." (PMID 38495105, 2024).
cancer (continued). "Furthermore, we examined the expression of PHLDA1 in HCC tissues derived from 46 patients in Sichuan Cancer Hospital and got informed consent from each patient." (PMID 38780041, 2024). "The mechanism of PHLDA1 transcriptional repression described in this study may therefore be a common resistance mechanism to targeted therapies for RTK-driven cancers." (PMID 37047202, 2023). "We further aligned with the reported human cancer‐related genes and found that PHLDA1, a gene located in the common B‐to‐A compartment of chromosome 12, was significantly upregulated in both cancer cell lines (BxPC3:Log2FC 2.33, q‐value < 0.001; PANC1: Log2FC 1.94, q‐value < 0.001)." (PMID 35570408, 2022). "Thus, treatment of cancer cells with ERK pathway-inhibitors enhances AKT activity mainly through PHLDA1/2 downregulation." (PMID 35831322, 2022). "Studies have suggested that PHLDA1 is involved in many biological processes, such as cell proliferation, cell differentiation, cell death, cancer metastasis, epithelial–mesenchymal transition, and cancer stem cell properties." (PMID 35237256, 2022). "Furthermore, human cancer cells harboring various oncogenes strongly expressed both PHLDA1/2 proteins." (PMID 35831322, 2022). "There have been several studies regarding PHLDA1's role in human cancers." (PMID 32983961, 2020). "Due to its importance in apoptosis, PHLDA1 has attracted a lot of attention in cancer biology." (PMID 29736818, 2018). "Finally, we have extrapolated our findings to other RTK-driven cancers, using cell-based, in vivo and bioinformatics approaches, to identify PHLDA1 as a mediator of resistance with direct relevance to a broad range of RTK-targeted therapies." (PMID 29490281, 2018). "Genes associated with the most common VELs included novel genes and several known oncogenes and tumour suppressors implicated in CRC as well as other forms of cancer, including MYC10, 16, BMP4 (refs 17, 18), PHLDA1 (refs 19, 20, 21, 22), SOX9 (refs 23, 24, 25) and TRIB3 (refs 26, 27)." (PMID 28169291, 2017). "Additionally, PHLDA1 and the quantity of activated mast cells in practically all cancer types showed a strong positive connection, according to immune infiltration study, indicating that mast cells may contribute to the development of cancer." (PMID 40688078, 2025). "Conversely, the six downregulated genes (SERPINE1, TNFRSF12A, PHLDA1, RNASEK, PPIA, and G0S2) are involved in diverse cancer-related pathways." (PMID 40340807, 2025). "Based on information from the PrognoScan database, the predictive significance of PHLDA1, PHLDA2, and PHLDA3 expression levels for various cancer patients was also evaluated." (PMID 38921000, 2024). "Using the cBioPortal, we independently analyzed the genetic changes in PHLDA1, PHLDA2, and PHLDA3 in distinct cancer types and then provided a comparative report regarding the functional protein partners of glutaminases obtained using PPI network analysis." (PMID 38921000, 2024). "Our multiomics research showed that PHLDA1, PHLDA2, and PHLDA3 have various functions in the development of cancer and regulate the prognosis of patient’s cancer differently." (PMID 38921000, 2024). "More important, this group of genes also included genes whose roles in cancer have yet to be fully addressed (e.g., TM4SF1, TM4SF19, EMP1, PHLDA1, and PHLDA2)." (PMID 35831322, 2022). "The cancer tissues of 10 PAAD patients were stained with the CAB016160 antibody, and the results showed that the PHLDA1 indicator was positive in 7 of the 10 tissue samples." (PMID 36142223, 2022). "In particular, two AKT-inhibitor molecules, PHLDA1 and 2, are simultaneously upregulated by oncogenic ERK signaling, and mediate cancer-specific ERK-AKT crosstalk." (PMID 35831322, 2022). "In particular, the AKT-inhibitor molecules PHLDA1 and PHLDA2 are simultaneously upregulated by oncogenic ERK signaling and confer resistance to ERK pathway-targeted therapeutics on cancer cells." (PMID 35831322, 2022).
cancer (continued). "However, when the patients are treated with ERK pathway-targeted therapeutics, PHLDA1/2 levels are downregulated in cancer cells, leading to the unwanted enhancement of AKT activity and associated cell survival, and thereby to resistance to the anti-cancer agents." (PMID 35831322, 2022). "As demonstrated in the top DEGs, specifically cancer stem lineage clusters expressed high levels of stemness feature genes (MKI67, CD44, CD24, and PROM1) and key DEeRNAs (PHLDA1 and RASD1)." (PMID 36092920, 2022). "We therefore combined PHLDA1, DUSP4, and EPHA2 genes into an optimized signature henceforth referred to as “Carcinoma of the Ovary MEK/ERK Signature” (COMS)." (PMID 36362153, 2022). "Using Aurora A-as7 kinase, we have identified several direct targets, including PHLDA1, LIMK2, ALDH1A1, SPOP, YBX1, and TWIST1, in cancer cells." (PMID 34066036, 2021). "Though we have claimed before, the researches on functions of PHLDA1 in HCC was poorly reported, several testes have showed multiple potentials of PHLDA1 in other cancers, especially the promotion of apoptosis." (PMID 33033502, 2020). "Furthering the scope of lower PHLDA1 expression levels attributed to RTKi therapy resistance, the authors studied another RTK-driven cancer, human epidermal growth factor receptor 2 (HER2) positive breast cancer." (PMID 32429563, 2020). "Thus, PHLDA1 may represent a useful biomarker to identify patients who will develop resistance to cancer therapeutics, and targeting PHLDA1 regulation presents an attractive prospect for preventing drug resistance in cancer patients." (PMID 29490281, 2018). "Here, we show that PHLDA1 downregulation is critical to acquisition and maintenance of drug resistance in RTK-driven cancer." (PMID 29490281, 2018). "A negative correlation was found between PHLDA1 and anti-cancer drugs such as docetaxel and gemcitabine, as researched in the GSCALite database." (PMID 39630301, 2025). "According to these findings, PHLDA1, PHLDA2, and PHLDA3 may partially co-express to control the prognosis of cancer." (PMID 38921000, 2024). "Our study of the underlying mechanism of cancer prognosis concerning pleckstrin expression may be aided by the finding that the patterns of PHLDA1, PHLDA2, and PHLDA3 co-expression regulated the clinical outcomes of individuals with certain types of cancer." (PMID 38921000, 2024). "Although there has been great advancement over the past decade in the detection and treatment of cancer development and prognosis, there is not enough research on the relationship between PHLDA1 expression and prognosis in some tumors." (PMID 38921000, 2024). "Since PHLDA1/2, which inhibit AKT, are specifically upregulated in cancer cells, the retention of their increased expression is an ideal therapeutic target to enable cancer-specific AKT inhibition." (PMID 35831322, 2022). "We found that the combination treatment of trametinib with bortezomib prevented trametinib-induced PHLDA1/2 downregulation and the subsequent AKT transactivation in cancer cells, thereby exerting a synergistic potent anti-cancer effect sufficient to induce apoptosis." (PMID 35831322, 2022). "Importantly, while single expression of either PHLDA1 or 2 exhibited only a marginal effect on AKT activity, their combined expression profoundly repressed it in cancer cells." (PMID 35831322, 2022). "Results of external validation in eRic database showed the specific chromatin localization and target genes of the four key DEeRNAs (CCR1, CD3D, PHLDA1, and RASD1), as well as potential drugs that may target these DEeRNAs in different cancers." (PMID 36092920, 2022). "However, the proteasome inhibitors MG132 and bortezomib, which also provoke ER stress, significantly upregulated PHLDA1 and PHLDA2 protein and mRNA expression in HEK293 and in various cancer cells." (PMID 35831322, 2022).
cancer (continued). "Since AKT signaling promotes cell survival, the ERK pathway-targeted drug-induced PHLDA1/2 downregulation and consequent AKT activation may prevent apoptosis of cancer cells and confer resistance to such anti-cancer agents." (PMID 35831322, 2022). "Ectopic expression of inducible full-length PHLDA1 in the RTKi resistant cancer cells re-sensitized the cells to RTKi therapy while ectopic expression of a PH domain mutant PHLDA1 did not re-sensitize cells to RTKi therapy." (PMID 32429563, 2020). "Collectively, these findings indicate that co-expression of PHLDA1/2 exerts a synergistic effect on the inhibition of AKT activity, and that oncogene-induced hyperactivation of ERK signaling represses AKT activation in human cancer mainly through the simultaneous induction of PHLDA1/2." (PMID 35831322, 2022). "PHLDA1 downregulation was proved to promote acquisition and maintenance of drugs resistance targeting receptor tyrosine kinase, which might suppress the effect of trastuzumab treatment on ERBB2 amplification cancers." (PMID 36010842, 2022). "Thus, PHLDA1/2 are induced by various ERK-activating oncogenes and might therefore be overexpressed in various human cancers." (PMID 35831322, 2022). "Thus, PHLDA1/2 can serve as potential biomarkers for human cancers with ERK-activating oncogenes and may play roles in the pathophysiology of human cancers." (PMID 35831322, 2022). "Although METTL3 is reported to promote translation in human cancer cells independent of its catalytic activity and m6A readers, the METTL3 knockdown resulted in a better association of our candidate mRNAs with polysomes, especially PHLDA1, PIDD1 and PMAIP1, under cisplatin treatment conditions." (PMID 36497162, 2022). "We also showed here that PHLDA1/2 are simultaneously induced by oncogenic, but not by physiological ERK signaling, and that both proteins are indeed upregulated in various human clinical cancers." (PMID 35831322, 2022).
infection (4 papers, 2018 to 2024). The state of being infected such as from the introduction of a foreign agent such as serum, vaccine, antigenic substance or organism. "Through the process of gene therapy for disease rescue, lentiviral vectors infection induces the up-regulation of PHLDA1 expression, which may cause some potential safety risks, including the possibility of promoting tumorigenesis and leading to adverse prognosis." (PMID 39012348, 2024). "Pleckstrin homology-like domain family A member 1 (PHLDA1) was rescued significantly by the application of MG132 during mock infection, and this may have made the rescue ratio (which is a ratio of ratios) less precise." (PMID 30122656, 2018).
cardiac disease (1 paper, 2018). "However, there are no reports of PHLDA1 action in cardiac disease." (PMID 29736818, 2018).
neurodegenerative disease (1 paper, 2023). A disorder of the central nervous system characterized by gradual and progressive loss of neural tissue and neurologic function. "In MPTP-induced mice, PHLDA1 deficiency also showed marked activity in inhibiting neuroinflammatory reactions and ameliorating the behavioral impairment of mice, highlighting the potential of PHLDA1 in treating neurodegenerative diseases." (PMID 38201283, 2023).
PHLDA1 also shares sentences with these, for which no sentence is quoted: basal cell carcinoma (3 papers); depression (3); bladder cancer (2); breast adenocarcinoma (2); ischemic cardiomyopathy (2); microcystic adnexal carcinoma (2); acute myeloid leukemia (1); Anxiety (1); atrial fibrillation (1); cervical carcinoma (1); Chronic colitis (1); coronary heart disease (1); cryptorchidism (1); diabetes (1); Dystonia (1); eczema (1); endothelial dysfunction (1); gestational diabetes mellitus (1); glaucoma (1); hay fever (1); head and neck squamous cell carcinoma (1); keloid (1); leukemia (1); lung squamous cell carcinoma (1); lymphoma (1); meningioma (1); myeloma (1); non-small cell lung carcinoma (1); nonalcoholic fatty liver disease (1); overnutrition (1).
A further 16 diseases each share a sentence with PHLDA1 in 1 paper.